CGAS (cyclic GMP-AMP synthase)
Diseases named in the same sentence as CGAS in open-access papers (continued):
Sharing a sentence is not in itself a finding about the gene and the disease.
Cirrhosis (1 paper, 2025). A chronic disorder of the liver in which liver tissue becomes scarred and is partially replaced by regenerative nodules and fibrotic tissue resulting in loss of liver function. "Collectively, our results suggest a crucial role of the hepatic EVs‐induced cGAS–STING pathway in promoting muscle injury during cirrhosis." (PMID 39804962, 2025). "Elevated ISG expression was also identified in the muscle tissues of the BDL group, suggesting that cirrhosis‐derived EVs may promote muscle inflammation by activating the cGAS‐STING pathway." (PMID 39804962, 2025). "In brief, we disclose that, during cirrhosis, EVs derived from injured hepatocytes containing abundant damaged mitochondrial contents (such as mtDNA) can promote skeletal muscle inflammation and atrophy by activating the cGAS‒STING pathways in muscle macrophages." (PMID 39804962, 2025).
corneal infection (1 paper, 2021). A viral or bacterial infectious process affecting the cornea. "Indeed, both cGAS and STING-deficient mice displayed increased weight loss, hydrocephalus and decreased survival following corneal infection with a neuroinvasive strain of HSV-1." (PMID 34010139, 2021).
cutaneous leishmaniasis (1 paper, 2022). Leishmaniasis affecting the skin. "Collectively, these results suggest that leishmania parasites might hijack the cGAS-STING-TBK1 signaling pathway to their own advantage and the TBK1 inhibitor amlexanox could be of interest as a candidate drug in treatment of cutaneous leishmaniasis." (PMID 36405710, 2022).
deafness (1 paper, 2024). An inherited or acquired condition characterized by the complete loss of the ability to hear from one or both ears. "Mammalian CLPP deletion triggers infertility, deafness, growth retardation, and cGAS-STING-activated cytosolic innate immunity." (PMID 38927630, 2024).
diabetic angiopathy (1 paper, 2024). "Intriguingly, previous research has implicated the cGAS‐STING pathway in diabetic angiopathy, which is associated with lipotoxicity‐induced mitochondrial dysfunction." (PMID 39365284, 2024).
E. coli infection (1 paper, 2025). "WB analysis demonstrated that E. coli infection markedly upregulated the expression of cGAS and Bax/Bcl2, along with the cleavage of caspase 3 and phosphorylation levels of STING, TBK1, IκBα, and P65." (PMID 41302013, 2025).
endometriosis (1 paper, 2024). The growth of functional endometrial tissue in anatomic sites outside the uterine body. "The understanding of how the cGAS-STING signaling pathway influences endometriosis requires further exploration." (PMID 39445027, 2024).
endometritis (1 paper, 2025). An acute or chronic, usually bacterial infectious process affecting the endometrium. "The previous study showed that in the patients with endometritis, the cyclic GMP–AMP synthase(cGAS)-STING pathway was activated and the expression of cytokine-encoding genes, including IL-1β, IL-8, IL-6 and IFN-β1 were increased." (PMID 39992946, 2025).
enterocolitis (1 paper, 2024). An inflammatory process affecting the small intestine and colon. "For example, in a murine model of enterocolitis (manifested by loss IL-10), experimental enterocolitis was less severe with cGAS-deficiency and was completely abrogated with STING-deficiency." (PMID 38881893, 2024).
eosinophilia (1 paper, 2025). "In contrast, cGAS−/− mice, and less prominently STING−/− mice exhibited reduced inflammatory phenotype characterized by lower total cell infiltration, eosinophilia, and Th2 cytokines or chemokines release in the airways." (PMID 40276777, 2025).
Erythema (1 paper, 2022). Redness of the skin, caused by hyperemia of the capillaries in the lower layers of the skin. "After two day, the erythema regression and duration times were also protracted by DDR inhibitors in the second round treatment, suggesting that low-dose IR might mount cGAS-mediated AIS via repairable DNA." (PMID 36402783, 2022).
Francisella tularensis infection (1 paper, 2017). "Recently, cGAS was shown to be crucial for STING dependent inflammasome responses to Francisella tularensis infection of macrophages." (PMID 28570638, 2017).
gastric tumors (1 paper, 2025). "Our study identifies TRIM6 as a critical negative regulator of the cGAS-STING innate immune pathway in MSS gastric tumors, revealing a potential therapeutic vulnerability." (PMID 40817248, 2025). "Conversely, elevated cGAS-STING signaling was identified in MSI-H and EBV-positive gastric tumors." (PMID 40817248, 2025).
gastritis (1 paper, 2025). Inflammation of the stomach. "PMMA nanoplastics activate the cGAS/STING pathway, promote the natural immune response, upregulate inflammatory markers, and induce gastritis." (PMID 40858547, 2025).
Glucose intolerance (1 paper, 2023). Glucose intolerance (GI) can be defined as dysglycemia that comprises both prediabetes and diabetes. "When fed HFD, cGAS-/- mice gain weight and display glucose intolerance." (PMID 37206668, 2023).
gout (1 paper, 2024). A condition characterized by painful swelling of the joints, which is caused by deposition of urate crystals. "The “Cytosolic DNA-sensing pathway” is enriched in the serum of gout patients, suggesting that targeting components of this pathway, such as cGAS-STING signaling, could dampen excessive inflammation." (PMID 39611154, 2024).
gynecological cancers (1 paper, 2025). "In this section, we explore the effects of different treatment strategies in targeting cGAS-STING pathway in gynecological cancers." (PMID 39949780, 2025). "Treatments against cGAS-STING pathway in gynecological cancers." (PMID 39949780, 2025). "The aim of our study will be to elucidate the complex interplay between various DNA damage response mechanisms and immune signaling pathways, with a focus on the activation and regulation of cGAS-STING, NF-κB, and related pathways in gynecological cancers." (PMID 39949780, 2025).
hearing loss (1 paper, 2025). "This study underscores the role of cGAS-STING in cisplatin ototoxicity and presents H-151 as a promising therapeutic for hearing loss." (PMID 39676140, 2025). "In addition, we found that cisplatin-induced mitochondrial dysfunction was accompanied by cytosolic DNA, which may act as a critical linker between the cyclic GMP-AMP synthesis−stimulator of interferon genes (cGAS-STING) pathway and the pathogenesis of cisplatin-induced hearing loss." (PMID 39676140, 2025).
helminth infection (1 paper, 2022). "However, little is known about the role of cGAS or type I IFN in the process of helminth infection." (PMID 35108342, 2022). "However, the function of cGAS in helminth infection is unclear." (PMID 35108342, 2022). "Although the function of cGAS-STING in protozoan infection has been characterized, little is known about the activation of this pathway in helminth infection." (PMID 35108342, 2022).
hemorrhage (1 paper, 2022). Loss of blood from the vascular compartment to the exterior or into nonvascular body space as a result of rupture or severance of the blood vessels. "Diffuse alveolar hemorrhage developed in an SLE mouse model is ameliorated by TANK via the suppression of type I IFN induced by cGAS-mediated sensing of intracellular DNA." (PMID 34819357, 2022).
Hydrocephalus (1 paper, 2021). Hydrocephalus is an active distension of the ventricular system of the brain resulting from inadequate passage of CSF from its point of production within the cerebral ventricles to its point of absorption into the systemic circulation. "cGAS−/− mice receiving diABZI-4 were protected from HSV-1–induced weight loss, lethality, hydrocephalus and symptoms of neurological disease." (PMID 34010139, 2021).
hypertensive heart disease (1 paper, 2023). Abnormal enlargement of the heart resulting from long-standing hypertension. "We examined iNOS expression, cytosolic mtDNA content and the status of the cGAS-STING cascade in myocardial sections from individuals with or without hypertensive heart disease." (PMID 37554263, 2023).
hypertrophic cardiomyopathy (1 paper, 2025). A condition in which the myocardium is hypertrophied without an obvious cause. "Here, the authors identify a mutation in the gene NAP1L1 to be associated with cases of hypertrophic cardiomyopathy, linking it to cGAS-STING-IFN signaling." (PMID 40169585, 2025).
Hypoglycemia (1 paper, 2022). A decreased concentration of glucose in the blood. "Interestingly, we observed that the cGAS–STING pathway was not significantly elevated in recurrent hypoglycemia compared with acute hypoglycemia, unlike NLRP3-mediated pyroptosis." (PMID 35915611, 2022).
hypothyroidism (1 paper, 2024). Abnormally low levels of thyroid hormone. "Notably, 3,5-T2, but not T3, reversed the hypothyroidism-induced activation of the cGAS-STING inflammatory cascade." (PMID 39301315, 2024).
idiopathic scoliosis (1 paper, 2022). A scoliosis with no known cause. "To examine the roles of the cGAS-STING axis and NLRP3 inflammasome in IVD degenerative progression, we collected tissue samples from patients who underwent open spine surgery or lumbar discectomy surgery because of idiopathic scoliosis or lumbar disc herniation." (PMID 35145201, 2022).
immune deficiency (1 paper, 2022). "Since immune deficiency due to loss of cGAS/STING signalling is not described in the literature, it is not clear what pathology, if any, we should expect to see associated with COPI-mediated disease." (PMID 35484149, 2022).
Impaired glucose tolerance (1 paper, 2023). An abnormal resistance to glucose, i.e., a reduction in the ability to maintain glucose levels in the blood stream within normal limits following oral or intravenous administration of glucose. "Consistent with literature regarding chronic HFD, cGAS-/- mice fed a HFD displayed increases in body weight and impaired glucose tolerance." (PMID 37206668, 2023).
intracerebral hemorrhage (1 paper, 2025). A cerebrovascular disorder characterized by bleeding into one or both cerebral hemispheres including the basal ganglia and the cerebral cortex. "Our study demonstrates that AMG487-mediated inhibition of CXCR3 maintains blood–brain barrier integrity and enhances both short-term and long-term neurological deficits after intracerebral hemorrhage by suppressing the cGAS-STING/AIM2 signaling pathway in mice." (PMID 40781073, 2025).
intrahepatic cholangiocarcinoma (1 paper, 2025). A carcinoma that arises from the intrahepatic bile duct epithelium in any site of the intrahepatic biliary tree. "In several IDH1-mutant cancers, including intrahepatic cholangiocarcinoma (ICC), glioma, melanoma, chondrosarcoma, and prostate cancer, this includes the epigenetic repression of cGAS, a DNA sensor critical for activating the STING pathway and type I interferon signalling." (PMID 40931345, 2025).
ischemic disease (1 paper, 2023). Lack of blood supply to an area of the body, resulting in impairment of tissue oxygenation. "The cGAS-STING pathway, initially extensively researched in the context of pathogenic infections, has been identified as a significant factor in various ischemic diseases." (PMID 37915571, 2023). "Additionally, increased levels of dsDNA in damaged cells have been observed to activate the cGAS-STING pathway in various ischemic diseases, leading to downstream IFNs and other pro-inflammatory cytokines that can mediate necroptosis, such as intestinal and renal ischemia." (PMID 37915571, 2023).
joint disorders (1 paper, 2024). "The cGAS-STING pathway, responsible for sensing cytoplasmic DNA and triggering inflammatory responses, plays a crucial role in the progression of these joint disorders." (PMID 38765007, 2024).
Kawasaki disease (1 paper, 2024). A rare inflammatory disease characterized by an acute febrile, systemic, self-limiting, medium-vessel vasculitis primarily affecting children. "After applying the STING inhibitor, we further used a cGAS inhibitor to repeat the validation of inhibiting this pathway in a Kawasaki disease cell model." (PMID 38872145, 2024). "In conclusion, this study reveals that the cytoplasmic release of mtDNA and the activation of cGAS-STING play crucial roles in the inflammatory response in Kawasaki disease." (PMID 38872145, 2024). "In the pathological mechanisms of Kawasaki disease, mitochondrial damage and the activation of the cGAS-STING signaling pathway may play pivotal roles." (PMID 38872145, 2024). "Our present study concluded that mitochondrial DNA activates the cGAS-STING signalling pathway via mPTP release, which is involved in the inflammatory response in Kawasaki disease." (PMID 38872145, 2024). "The activation of the cGAS-STING pathway in clinical samples and Kawasaki Disease (KD) animal models has provided significant insights." (PMID 38872145, 2024).
laryngeal carcinoma (1 paper, 2023). Carcinoma that arises from the laryngeal epithelium. "Therefore, future analyses of downstream responder gene expression are needed to clarify whether laryngeal cancer exhibits functional cGAS–STING activation." (PMID 37444620, 2023). "The immunomodulatory effects of the DNA sensor cGAS and the cyclic GMP–AMP receptor stimulator of interferon genes (STING) signaling axis have been extensively studied in various types of cancer; however, their role in laryngeal cancer remains unknown." (PMID 37444620, 2023). "Targeting the cGAS–STING signaling pathway can potentially improve the activation of immune effector cells, although its role in the development and progression of laryngeal cancer has not yet been investigated in depth." (PMID 37444620, 2023). "The goal of this study was to evaluate the expression levels of cGAS and STING in the tumor cells of non-metastatic laryngeal cancer." (PMID 37444620, 2023). "Although the laryngeal cancer samples in this study demonstrated an inflamed phenotype with abundant intratumoral immune infiltrates, we did not observe a correlation between STING and cGAS expression at the protein level." (PMID 37444620, 2023). "Therefore, this study aimed to assess the expression levels of cGAS and STING in laryngeal cancer in both early and advanced non-metastatic stages of the disease." (PMID 37444620, 2023). "Modulation of the cGAS–STING signaling pathway has potential therapeutic benefits in different types of malignant tumors, and it is currently being investigated in numerous clinical studies, but its role in the development and progression of laryngeal cancer has not yet been investigated." (PMID 37444620, 2023).
Legionnaires' disease (1 paper, 2018). A pneumonia caused by Legionella pneumophila and other Legionella species, which is characterized by fever, cough, progressive respiratory distress, and which is often accompanied by extrapulmonary manifestations. "In a mouse model of Legionnaires’ disease, cGAS- and STING-deficient animals exhibited higher bacterial loads as compared to wild-type mice." (PMID 29298342, 2018). "Hence, sensing of bacterial DNA by the cGAS/STING pathway contributes to antibacterial defense against L. pneumophila infection, and the hypomorphic variant HAQ TMEM173/STING is associated with increased susceptibility to Legionnaires’ disease in humans." (PMID 29298342, 2018). "In summary, we show that cGAS/STING contributes to the antibacterial defense against L. pneumophila infection, reveal that the hypomorphic STING variant HAQ negatively affects the antibacterial immune response, and indicate that HAQ TMEM173/STING carriage predisposes to Legionnaires ‘disease." (PMID 29298342, 2018). "Here we tested the hypotheses that i) the cGAS/STING pathway mediates defense against L. pneumophila in mice and men, ii) that carriage of HAQ TMEM173/STING impairs the antibacterial immune response, and iii) that carriage of HAQ TMEM173/STING predisposes to Legionnaires’ Disease." (PMID 29298342, 2018).
lymph node metastases (1 paper, 2024). "We found that cGAS-STING scores were higher in the advanced-stage clinical subgroups in the METABRIC cohort, especially stage II and III&IV patients and patients with lymph node metastases (P < 0.001)." (PMID 38167507, 2024).
mesothelioma (1 paper, 2021). A usually malignant and aggressive neoplasm of the mesothelium which is often associated with exposure to asbestos. "Dotplot of IRF3 and the cGAS/STING signaling pathway genes showed that IRF3 and STING (TMEM173) were expressed in mesothelioma tumor cells, while TBK1 and CGAS expressed mainly in monocyte/macrophages." (PMID 34768716, 2021).
metastatic colorectal cancer (1 paper, 2025). "Previous studies have demonstrated that genetic variation in the cGAS-STING -mediated type I interferon pathway may influence the response to cetuximab in metastatic colorectal cancer." (PMID 41476984, 2025).
monocytic leukemia (1 paper, 2025). "To determine the role of endogenous gigaxonin in cGAS‐mediated antiviral immune responses, we established a stable gigaxonin‐knockdown human monocytic leukemia cell line, THP‐1, via shRNA transduction and treated the cells with HSV‐1 infection or herring testis‐DNA (HT‐DNA) transfection." (PMID 40936183, 2025).
Mycobacterium infection (1 paper, 2017). Infections with bacteria of the genus Mycobacterium. "In addition to cGAS and AIM2, we here established a role of another DNA sensor, IFI204, during mycobacterium infection." (PMID 28529930, 2017).
myeloid malignancies (1 paper, 2020). "For example, chronic activation of the cGAS-STING pathway may promote the pathogenesis of myeloid malignancies or induce an adaptive immunodeficiency." (PMID 33329537, 2020). "Gain-of-function mutations or aberrant activation of the cGAS-STING pathway may participate in the pathogenesis of myelopoiesis-associated clonal hematopoiesis and myeloid malignancies." (PMID 33329537, 2020).
neuritis (1 paper, 2024). A neuropathy arising from inflammation of one or more nerves. "Biomarkers of AD-associated neuritis include NF-κB and cGAS-STING pathway." (PMID 39258145, 2024).
neurological autoimmune diseases (1 paper, 2022). "Therefore, how to effectively regulate the cGAS-STING signaling using a cGAS or STING modulator is key to the treatment of neurological autoimmune diseases." (PMID 36172373, 2022).
orchitis (1 paper, 2021). Inflammation of one or both testes due to viral or bacterial infections. "In summary, our present study provides compelling evidence that PM-induced orchitis in mice may be amenable to aspirin pre-treatment by acetylating cGAS." (PMID 34925318, 2021).
osteomyelitis (1 paper, 2025). An acute or chronic inflammation of the bone and its structures due to infection with pyogenic bacteria. "While such responses might contribute to inflammatory bone loss, RIG-I- and cGAS-dependent type I IFN production may serve a protective role during osteomyelitis by restricting S. aureus survival and/or replication in infected osteoblasts and osteoclasts." (PMID 40135931, 2025). "Finally, we have begun to establish the biological significance of RIG-I- and cGAS-mediated bone cell responses with the demonstration that their attenuation increases S. aureus burden in infected cells, suggesting a potentially protective role for these sensors in osteomyelitis." (PMID 40135931, 2025).
paraganglioma (1 paper, 2022). A benign or malignant neoplasm arising from paraganglia located along the sympathetic or parasympathetic nerves. "Higher cGAS-STING score was closely associated with poor clinical outcome of kidney renal clear cell carcinoma (KIRC) and kidney renal papillary cell carcinoma (KIRP), whereas the cGAS-STING score predicted a better prognosis in pheochromocytoma and paraganglioma (PCPG)." (PMID 35983076, 2022).
periodontal disease (1 paper, 2026). "The cGAS/STING pathway plays a key role in innate immune responses and has been implicated in inflammation-associated bone loss in periodontal disease." (PMID 41597400, 2026).